CCR2 (C-C motif chemokine receptor 2)
Diseases named in the same sentence as CCR2 in open-access papers (continued):
Sharing a sentence is not in itself a finding about the gene and the disease.
influenza infection (continued). "Wang and colleagues demonstrated that priming with Staphylococcus aureus, which commonly colonizes the upper respiratory mucosa, attenuated influenza-mediated lung injury via TLR2 signaling that recruited peripheral CCR2+CD11b+ monocytes into the alveoli." (PMID 25250029, 2014). "Lohmeyer's group showed that during infection of mice with PR/8 influenza, CCR2+ monocytes which were recruited to the lung and became exudate macrophages were mediating this cell death." (PMID 23304058, 2012). "Although other chemokines such as MCP-2, MCP-3, and MCP-4 also contribute to attract CCR2-expressing monocytes after influenza infection, overexpression of MCP-1 results in elevated monocyte recruitment." (PMID 21383977, 2011). "In our study, however, Ly6Cint monocytes generated in influenza-infected Ifnar1−/− mice expressed high levels of CCR2." (PMID 21383977, 2011). "The dual fate of CMo as suggested by our study is supported by previous fate mapping studies demonstrating that Ly6Chi CMo differentiate into IM and that AM recruited into the alveolar space following influenza infection originate from CCR2-dependent bone marrow-derived monocytes." (PMID 38348034, 2024). "Similarly, CCR2-dependent recruitment of monocytes-derived DCs has also been reported upon influenza infection, exposure to LPS and particulate antigens." (PMID 34305885, 2021). "It was previously shown that CCL2 recruits CCR2+ inflammatory monocytes to the lung during severe influenza infection and prophylactic use of CCR2 antagonist reduces pulmonary immunopathology, markedly improving the survival of influenza infected mice." (PMID 32766256, 2020). "Mechanistically, the beneficial effect of Flt3-L might be due to the reduced recruitment of CCR2+ inflammatory monocytes, a cell population involved in lung epithelial damage and bacterial dissemination post-influenza." (PMID 30372491, 2018). "To exclude the possibility of CCR2-independent recruitment of inflammatory monocytes into coinfected lungs, we confirmed the near absence of these cells 2 days into the bacterial infection, at day 7 post-influenza infection (Fig2I)." (PMID 26265006, 2015). "In the light of our results, CCR2 blockade even after influenza exposure may have a beneficial effect as it may reduce the risk of subsequent bacterial infection." (PMID 26265006, 2015). "We showed that smoke-exposed CCR2-deficient mice did not have attenuated inflammation in response to influenza infection." (PMID 20967263, 2010). "However, these monocytes are dispensable in controlling influenza infection since in CCR2 deficient mice, lacking these infiltrating cells, the virus load was similar to the wild type mice when infected with the influenza virus at a sublethal dose." (PMID 35784329, 2022). "Thus, while the PPAR-gamma agonist, pioglitazone, significantly attenuated exaggerated inflammatory responses in smoke-exposed mice, a CCR2 deficiency did not appear to confer any beneficial effect on smoke-exposed influenza-infected animals." (PMID 20967263, 2010). "The findings demonstrated that the mRNA levels of CCR5, CCR2, CCR1 and CXCR2 genes were increased after influenza infection." (PMID 37957672, 2023). "Influenza infection also modulates expression and chemotactic responsiveness of CCR1 and CCR2 in monocytes." (PMID 31041196, 2019). "During early influenza infection, airway epithelial cells produce CCL2 (MCP-1), which attracts CCR2+ monocytes into the lung tissue from the blood." (PMID 23304058, 2012). "In previous studies mice lacking SPP1 and CCL5 were found to clear influenza infection with no adverse effects, while mice lacking CCR2 survived infection by a mouse-adapted influenza A virus that killed wild-type mice." (PMID 22189154, 2011).
influenza infection (continued). "Recovery from influenza pneumonia can result in AM with increased surface MHC-II, and improved responses to subsequent bacterial infections including elevated induction of IL-6, which requires CCR2-mediated recruitment of monocytes that differentiate and replace the AM of embryonic origin." (PMID 35133985, 2022). "Similarly, CCL2 (Ccl2), a ligand for CCR2 that recruits CCR2+ inflammatory monocytes, as well as CXCL1 (Cxcl1), CXCL2 (Cxcl2), and CXCL5 (Cxcl5), which are ligands of CXCR2 that induce neutrophil infiltration in influenza-infected lungs, showed notable decreases in NOD.SCID mice." (PMID 37904257, 2023). "Lung-recruited neutrophils induced CCR1, CCR2, CCR3, CCR5, CXCR1, CXCR3, CXCR4, which were absent or marginally induced in peripheral blood neutrophils from influenza-infected mice." (PMID 31041196, 2019). "Both Ly6Chi and Ly6Cint monocytes obtained from the lung of WT and Ifnar1−/− mice expressed CCR2 but not CXCR2, suggesting the critical role of MCP-1 for monocyte recruitment into influenza-infected lung." (PMID 21383977, 2011). "Other studies in mice lacking CXCR2 or CCR2, the primary receptor of CCL2, have shown that blockade of chemokine signaling reduces pulmonary recruitment and subsequently reduces injury and improves survival following influenza infection." (PMID 24223177, 2013).
viral infection (29 papers, 2008 to 2026). "CCR2 blockade was also associated with the canonical pathways, the roles of lipids/lipid rafts in the pathogenesis of viral infections, and the roles of cytokines in mediating communication between immune cells were associated." (PMID 40353220, 2025). "To determine the role of moDCs in the fate determination of CD8+ T cells during acute viral infection, we used CCR2-deficient (Ccr2−/−) mice." (PMID 31474983, 2019). "While blocking mo-DC activity or deficiency in CCR2 improves survival and mitigates severe lung pathology in experimental virus infection, complete depletion of mo-DCs leads to uncontrolled virus spread and more severe disease." (PMID 26965109, 2016). "CCRs can also guide immunopathogenesis during virus infection where CCR2 deficient mice are protected from a lethal influenza virus infection due to the failure to recruit inflammatory monocytes to the infected lung." (PMID 19079579, 2008). "CCR5 and CCR2 are key players in the trafficking of lymphocytes and monocytes/macrophages and have been implicated in the pathophysiology of a number of diseases, including viral infections and complex disorders with an inflammatory component." (PMID 31377844, 2019). "During the viral infection, Gn is presumed to attach to the putative host cell receptor C-C motif chemokine receptor 2 (CCR2) to mediate viral entry." (PMID 38257828, 2024). "The chemokine receptors CCR5 and CCR2 are integral for mediating monocyte trafficking and inflammatory responses, and thus the distinct changes in the distribution of pregnancy-derived monocytes expressing these receptors could help to explain the differing susceptibility to viral infection." (PMID 37149573, 2023). "Our results provide insights into how innate immune sensing of viral infection by lung AECIIs influences the activation and differentiation of CCR2+ inflammatory monocytes to defend against pulmonary poxvirus infection." (PMID 35351885, 2022). "Recruitment of Ly6Chi monocytes to inflamed tissue or the dLN in response to viral infection is reportedly CCR2- and type I IFN-dependent." (PMID 31999809, 2020). "CCR2-mediated monocyte recruitment is crucial for the resistance to several viral infections, but it is deleterious and enhances pathology during influenza virus and HIV infections." (PMID 31377844, 2019). "Upon viral infection, Ly-6Chi monocytes enter inflamed tissues from the blood stream in a CCR2-mediated manner, and some of the infiltrated Ly-6Chi monocytes further differentiate into inflammatory DCs, which participate in innate and adaptive immunity." (PMID 29760708, 2018). "Elevated numbers of mo-DCs that express CCR2 (chemokine receptor for CCL2) or produce high amounts of TNF-α and NO are associated with greater morbidity and mortality in response to viral infection." (PMID 26965109, 2016). "Together, these data suggest that locally produced IL-10 enhances the recruitment of CCR2+ monocytes, which localize to areas of viral infection and reduce viral titers in the skin." (PMID 26991092, 2016). "Our results indicated that uncontrolled viral replication leads to excessive production of inflammatory innate immune responses by accumulating CCR2+ inflammatory monocytes, which contribute to the fatal outcomes of high pathogenicity virus infections." (PMID 25407417, 2014). "Likewise, studies employing CCR2 depleter mice result in the depletion of not only CCR2+ monocytes and CCR2+ mo-DCs during A. fumigatus lung infection (14, –, 16) but also potentially inf-cDC2s, as they depend on CCR2 for migrating to the lungs during viral infection." (PMID 40980891, 2025). "However, the current study uncovered a previously unappreciated role for CCR7 in iMO recruitment to the blood and brain during encephalitic viral infection and provides a more complete view of how CCR2 and CCR7 have complementary roles in this process under homeostatic conditions." (PMID 38658802, 2024).
viral infection (continued). "Expression of SFTSV receptors C‐C motif chemokine receptor 2 (CCR2) and lipoprotein receptor‐related protein 1 (LRP1) in pancreatic organoids supported viral infection." (PMID 41090515, 2026). "Flow cytometry of bone marrow revealed a significant reduction in CCR2-EGFP+ monocyte-derived cells, suggesting migration of these cells to the brain or cell death due to viral infection." (PMID 40688087, 2025). "Nevertheless, because cell-type distributions of C-type lectins and CCR2 are partially overlapped, SFTS virus infection in cells expressing both molecules (e." (PMID 39008518, 2024). "CCR2, the receptor of CCL2 has been reported to play a critical role in the recruitment of DCs and CD8+ T cells during viral infections." (PMID 34194439, 2021). "The marked increases in Ccr2, Ccr5, Pld1, and Ackr3 produced by either AMPH or EIH observed in vivo provide further insight into the initial immune system alterations that result from methamphetamine and AMPH abuse and could modify risk for HIV and other viral infections." (PMID 30779732, 2019). "CCR1, CCR2, and CCR5 upregulations could enhance lung infiltration by monocytes and macrophages upon viral infection and mediate hyperinflammation and organ damage in the aftermath." (PMID 36232655, 2022). "Moreover, in the absence of CCR2-mediated inflammatory myeloid cell recruitment, bites were unable to promote virus infection." (PMID 34035796, 2021). "Taken together, these data provide strong evidence that CCR2 and CCR7 play a synergistic role to mediate iMO recruitment during encephalitic virus infection, the latter of which has not been previously reported to be involved in iMO recruitment during viral infection." (PMID 38658802, 2024).
ovarian carcinoma (28 papers, 2012 to 2025). A malignant neoplasm originating from the surface ovarian epithelium. "On the other hand, a different group investigated CC chemokine-associated microenvironment in ovarian cancer stroma and ascites, and found defective CCR2 expression." (PMID 24213462, 2012). "This dual mechanism involving both the tumor cells’ autocrine signaling and macrophage recruitment contributes to the poor therapeutic response and highlights the potential benefit of CCR2 inhibitors in treating ovarian cancer." (PMID 40330466, 2025). "We also show that CCR2 armored CAR-T cells improve trafficking in a disseminated peritoneal model of ovarian cancer." (PMID 41424784, 2025). "The activated M2 macrophage released CCL13, binding to CCR2 and thus promoted ovarian cancer tumour growth and metastasis in vitro and in vivo." (PMID 38680032, 2024). "In this study, we identified a previously unrecognized role of BETi in overcoming adaptive resistance to AVA therapy in ovarian cancer by selectively targeting CCR2+ macrophages." (PMID 35094142, 2022). "The enhanced metastasis and invasion of ovarian cancer cells can be eliminated by blocking CCL2/CCR2 signaling transduction with CCL2 neutralizing antibodies or a CCL2 gene knockout defect." (PMID 36403055, 2022). "Adipocytes secrete monocyte chemotactic protein-1 (MCP-1) to bind C-C motif chemokine receptor 2 (CCR-2) on ovarian cancer cells to activate the PI3K/AKT/mTOR pathway, thereby increasing the expression of HIF-1α, which contributes to ovarian cancer metastasis." (PMID 35004308, 2021). "It has been reported that CCL5-induced invasion of ovarian cancer stem-like cells is mediated by CCR1 and CCR3, and CCR3, along with CCR2 and CCR5, are associated with CCL11-stimulated proliferation, migration, and invasion of ovarian cancer cells." (PMID 34206004, 2021). "The overexpression of CCR2 shortens overall and progression‐free survival in patients with ovarian cancer." (PMID 34464477, 2021). "Consistently, we have observed that doxorubicin (Dox)-loaded M1 macrophages are able to find out spreading ovarian cancer cells with the help of upregulated cell surface protein C-C chemokine receptor type 2 (CCR2) 13,14." (PMID 32550891, 2020). "It has been shown that the CCL2/CCR2 axis is a determinant of the degree of macrophage infiltration in ovarian cancer." (PMID 24384839, 2013). "Examples of CCL2/CCR2 axis antagonists undergoing early phase clinical trials include trabectedin, a CCL2 antagonist used to treat ovarian cancer, and cenicriviroc, a CCR2 (and CCR5) inhibitor currently progressing through clinical trials for MASH and fibrosis." (PMID 39684877, 2024). "Next, we explored whether CCR2 was involved in the enhanced effect of CCL13 on ovarian cancer cell growth in vitro." (PMID 38680032, 2024). "Furthermore, we verified that CCR2 was the receptor of CCL13 when ovarian cancer with oestrogen treatment." (PMID 38680032, 2024). "Moreover, the ability of ovarian cancer cells to adhere to M-Met5A cells was decreased by CCR2 and/or CCR5 antagonists." (PMID 36766725, 2023). "CCR2 might make a difference in enhancing the ability of ovarian cancer cell peritoneal metastasis and portending a poor prognosis." (PMID 35756990, 2022). "Inhibition of the CCL2/CCR2 axis using a CCR2 inhibitor significantly increased paclitaxel sensitivity in both in vitro and in vivo models, suggesting that targeting this signaling pathway could be a promising therapeutic strategy to overcome chemoresistance in ovarian cancer." (PMID 40330466, 2025). "A high M1/M2 ratio correlates with better prognosis and platinum sensitivity in ovarian cancer patients, while ABBV-075’s ability to downregulate CCR2 expression in macrophages disrupts the MSMP/CCR2-mediated adaptive resistance to AVA." (PMID 41029427, 2025). "To further confirm that CCR2 was involved in oestrogen‐induced exosomes on ovarian cancer tumour growth, we introduced RS504393, a CCR2 antagonist." (PMID 38680032, 2024).
ovarian carcinoma (continued). "Our findings indicate a previously unrecognized role for BETi in selectively targeting CCR2+ TAMs and enhancing the efficacy of AVA therapy in ovarian cancer." (PMID 35094142, 2022). "Collectively, the bioinformatics analysis of TCGA data indicated that expression of CCR2 and its ligand MSMP was related with macrophage infiltration in ovarian cancer." (PMID 35094142, 2022). "Our findings suggested a previously unrecognized role for BETi in selectively targeting CCR2+ macrophages and enhancing the efficacy of AVA therapy in ovarian cancer." (PMID 35094142, 2022). "Binding to its cognate receptor CCR2, CCL2 expedited the migration and invasion of ovarian cancer cells and improved cisplatin resistance." (PMID 36403055, 2022). "They found that CD3+CD4+ T cell populations and CD14+ macrophages in the ascites preferentially express CCR2 and CC5R, suggesting that they play important roles in CC chemokine networks of ovarian cancer ascites." (PMID 24213462, 2012). "To overcome the resistance to BEV in patients with ovarian cancer, we performed a validation study of combination therapy with BEV (10 mg/kg) and the CCR2 inhibitor BMS CCR2 22 (20 mg/kg) (BEV/CCR2i) using 3 consecutive patient‐derived xenografts (PDXs) of immunodeficient mice." (PMID 36810973, 2023). "Macrophages isolated from both the ascitic fluid and solid tumor from ovarian cancer patients exhibited very low levels of CCR2 mRNA, which correlated with the lack of chemotactic response to CCL2." (PMID 24384839, 2013). "In this study, we sought to investigate the role of MSMP/CCR2 signaling in macrophage polarization and the effects of targeting CCR2+ macrophages with bromodomain and extra-terminal domain (BET) inhibitors (BETi) in ovarian cancer, especially in the context of enhancing the efficacy of AVA therapy." (PMID 35094142, 2022). "In addition, the CCR2 inhibitor did not affect OC-MQ-stimulated invasion of ovarian cancer cells (data not shown)." (PMID 34206004, 2021).